MIR423 (microRNA 423)
Synonyms: hsa-mir-423; MIRN423; mir-423
Gene: MicroRNA gene on chromosome 17 (30,117,079 to 30,117,172, forward strand). Ensembl gene ENSG00000283935.
Gene Ontology:
Biological process: miRNA-mediated post-transcriptional gene silencing
Cellular component: RISC complex